BCL6 (BCL6 transcription repressor)
Description:
Transcriptional repressor mainly required for germinal center (GC) formation and antibody affinity maturation which has different mechanisms of action specific to the lineage and biological functions. Forms complexes with different corepressors and histone deacetylases to repress the transcriptional expression of different subsets of target genes. Represses its target genes by binding directly to the DNA sequence 5'-TTCCTAGAA-3' (BCL6-binding site) or indirectly by repressing the transcriptional activity of transcription factors. In GC B-cells, represses genes that function in differentiation, inflammation, apoptosis and cell cycle control, also autoregulates its transcriptional expression and up-regulates, indirectly, the expression of some genes important for GC reactions, such as AICDA, through the repression of microRNAs expression, like miR155. In follicular helper CD4(+) T-cells (T(FH) cells), promotes the expression of T(FH)-related genes but inhibits the differentiation of T(H)1, T(H)2 and T(H)17 cells. Also required for the establishment and maintenance of immunological memory for both T- and B-cells. Suppresses macrophage proliferation through competition with STAT5 for STAT-binding motifs binding on certain target genes, such as CCL2 and CCND2. Besides, also controls neurogenesis through the alteration of the composition of NOTCH-dependent transcriptional complexes at selective NOTCH targets, such as HES5, including the recruitment of the deacetylase SIRT1 and resulting in an epigenetic silencing leading to neuronal differentiation.
Synonyms: BCL5; LAZ3; ZBTB27; ZNF51; BCL6A
Tractability: Small molecule: a structure with a bound ligand is known; a high-quality ligand is known; it has a binding pocket of medium quality. PROTAC: it is named in the literature on targeted protein degradation; UniProt records ubiquitination sites on it; ubiquitination databases record sites on it; a small molecule that binds it is known.
Target class: Transcription factor
Chemical probes: BI-1136 (high quality), BI-3802 (high quality), BI-3812 (high quality), CCT369260 (high quality), CCT374705, OICR11029 (high quality), PD134388, TMX-2164 (high quality), TP-021 (high quality)
Gene: Protein-coding gene on chromosome 3 (187,721,377 to 187,745,725, reverse strand). Ensembl gene ENSG00000113916.
Subcellular location: Nucleus
Subcellular location (Human Protein Atlas): Nucleoplasm; Golgi apparatus
Pathways (Reactome):
Gene expression (Transcription): FOXO-mediated transcription of cell death genes
Immune System: Interleukin-4 and Interleukin-13 signaling
Gene Ontology:
Molecular function: chromatin binding; DNA-binding transcription factor activity; DNA-binding transcription factor binding; DNA-binding transcription repressor activity, RNA polymerase II-specific; identical protein binding; protein binding; sequence-specific DNA binding; sequence-specific double-stranded DNA binding; transcription corepressor binding; RNA polymerase II cis-regulatory region sequence-specific DNA binding; chromatin DNA binding; intronic transcription regulatory region sequence-specific DNA binding; RNA polymerase II transcription regulatory region sequence-specific DNA binding
Biological process: DNA damage response; negative regulation of cell growth; negative regulation of DNA-templated transcription; negative regulation of transcription by RNA polymerase II; positive regulation of apoptotic process; positive regulation of regulatory T cell differentiation; negative regulation of B cell apoptotic process; negative regulation of mitotic cell cycle DNA replication; regulation of cell differentiation; regulation of cell population proliferation; regulation of cytokine production; regulation of germinal center formation; regulation of immune response; regulation of immune system process; regulation of inflammatory response; type 2 immune response; positive regulation of cell differentiation; positive regulation of lymphocyte activation; regulation of apoptotic process; regulation of leukocyte cell-cell adhesion; regulation of T cell differentiation
Cellular component: nucleoplasm; nucleus; paraspeckles; replication fork
Genetic constraint (gnomAD): Loss-of-function variants: 7 observed, 59.42 expected, observed/expected ratio (o/e) 0.12, 90% interval 0.066 to 0.22. The upper end of that interval is the gene's LOEUF score, 0.22, which puts it in group 1 of 6, group 1 being the genes least tolerant of losing a copy. Missense variants: 685 observed, 977.52 expected, observed/expected ratio (o/e) 0.7, 90% interval 0.66 to 0.75. Synonymous variants: 339 observed, 366.03 expected, observed/expected ratio (o/e) 0.93, 90% interval 0.85 to 1.01.
Homologues: Orthologues: chimpanzee BCL6 (99% identical), macaque BCL6 (98% identical), guinea pig BCL6 (96% identical), rabbit BCL6 (95% identical), rat Bcl6 (95% identical), pig BCL6 (95% identical), mouse Bcl6 (95% identical), dog BCL6 (94% identical), tropical clawed frog bcl6 (68% identical), zebrafish bcl6aa (61% identical), zebrafish bcl6ab (41% identical). Paralogues in human: BCL6B (37% identical), ZBTB21 (18% identical), ZBTB46 (18% identical), ZBTB49 (17% identical), ZBTB12 (15% identical), ZBTB3 (15% identical), ZBTB14 (15% identical), ZBTB7B (14% identical), ZBTB26 (14% identical), ZBTB6 (14% identical), NACC2 (12% identical), FEZF1 (12% identical), and 16 more.
Diseases named in the same sentence as BCL6 in open-access papers:
BCL6 is named in the same sentence as 297 diseases in open-access papers, as found by Europe PMC text mining. Sharing a sentence is not in itself a finding about the gene and the disease. The quoted sentences say what the papers report.
lymphoma (415 papers, 1997 to 2026). A malignant (clonal) proliferation of B- lymphocytes or T- lymphocytes which involves the lymph nodes, bone marrow and/or extranodal sites. "The essential role BCL6 plays in B cell development can be coopted by malignant cells such that it serves as an oncogene in GC-derived lymphomas, with high mutation rates and translocation in DLBCL." (PMID 40070829, 2025). "Given the transformed immunophenotype and molecular risk (MYC/BCL6, high Ki-67), aggressive combination therapy similar to other double-hit lymphomas is warranted." (PMID 41146768, 2025). "C-MYC rearrangements, especially when concurrent with BCL2 and/or BCL6 rearrangements (double-hit or triple-hit lymphomas), are strongly associated with a very poor prognosis." (PMID 40062071, 2025). "BCL2 overexpression is associated with an increased risk of lymphoma, whereas BCL6 plays a crucial role in maintaining germinal center B cells." (PMID 40563566, 2025). "Prognosis is influenced by stage, Integrated Pulmonary Index (IPI) score, molecular subtype, and genetic rearrangements such as MYC, BCL2, or BCL6, with double-hit lymphomas associated with poorer outcomes." (PMID 41450358, 2025). "In the present study, we observed that mice with endothelial Fbw7 deletion spontaneously developed DLBCL, with FBW7 deficiency and Bcl6 accumulation in lymphoma tissue." (PMID 38485719, 2024). "Both ABC and GCB lymphoma cells are affected by the aberrant expression of BCL6, but the GCB subtype is hit by particular mutations." (PMID 39518937, 2024). "It is also present in 15%-30% of DLBCL patients, who are often associated with BCL-2 or BCL-6 translocations, leading to "double-hit" lymphoma." (PMID 39583511, 2024). "This rearrangement can also be associated with BCL2 and/or BCL6 translocation—with such ‘double-’ or ‘triple-hit’ lymphomas considered high grade in the WHO classification." (PMID 35882984, 2023). "BCL2 expression is one of the most influential alterations in DLBCL and is already prognostically significant, as DLBCL with MYC and BCL2/BCL6 mutations are termed double hit or triple hit lymphomas and are associated with a worse prognosis." (PMID 36818048, 2023). "The reason for this is that aggressive lymphomas with a MYC/BCL2 double hit form a homogeneous group with respect to GEPs and the mutational profile, whereas MYC/BCL6 DH lymphomas are heterogeneous in nature." (PMID 37190213, 2023). "miR-155 expression in mice B cells causes pre-B cell proliferation and high-grade lymphoma or leukemia by repressing B cell lymphoma-6 (Bcl6) with different mechanisms, including HDAC4 repression." (PMID 36762207, 2023). "Further characterisation of high-grade B-cell lymphoma achieved by next-generation sequencing, and mutations of MYC and BCL2 and/or BCL6 genes (“double-hit”-DHIT or “triple-hit”-THIT lymphoma) have been associated in various studies with a worse prognosis." (PMID 37240953, 2023). "In these experiments, Hdac3 deficiency rescued repression of the Crebbp/BCL6-regulated transcripts and suppressed Crebbp-mutant lymphomas in vitro and in vivo." (PMID 38124747, 2023). "Expression of miR-155 in mouse B cells causes proliferation of pre-B cells and high-grade lymphoma or leukemia by suppressing B cell lymphoma-6 (Bcl6) via various mechanisms, including HDAC4 downregulation." (PMID 36762207, 2023). "It is frequently mutated or deleted in lymphomas of germinal centre origins leading to increased BCL-6 levels." (PMID 36977592, 2023). "One possibility is thus that ectopic expression of BCL6 induced by the translocation in marginal zone B cells cooperates with other “marginal zone” genes to ultimately cause this type of lymphoma." (PMID 34456919, 2021). "More critically and consistent with the observed aggressive tumor phenotype, Smc3/Bcl6 lymphomas featured induction of canonical GC-associated MYC target gene sets." (PMID 34621263, 2021).
lymphoma (continued). "Further studies utilizing CG-806 in combination with venetoclax show inhibition of driver and rescue pathways within in-vivo studies using double/triple hit lymphoma cell lines that harbor MYC/BCL2/BCL6 mutations, yielding promising results." (PMID 34829820, 2021). "Strikingly, this reduction in Tet2 promoter to enhancer looping was associated with reduced abundance of Tet2 mRNA in Smc3/Bcl6 vs Bcl6 lymphomas from qPCR experiments performed in independent lymphoma specimens." (PMID 34621263, 2021). "In lymphoma, high expression levels of BCL6 were reported to be associated with pro-survival and proliferation functions." (PMID 32817744, 2020). "DLBCL associated with translocation of MYC and BCL2 and/or BCL6 (double-hit or triple-hit lymphomas) needs to be investigated in the context of high risk for CNS relapse of primary breast DLBCL." (PMID 32781541, 2020). "Since FBXO11 has been demonstrated to mediate ubiquitination of BCL6 in lymphoma, it is reasonable to attempt to rescue FBXO11 loss through inhibition of proteasomal degradation." (PMID 33024076, 2020). "DLBCL cases with dual rearrangement of MYC and BCL2 and/or BCL6, frequently named “double-hit” lymphomas, are associated with significantly shorter survival and have been reclassified as a new group of lymphomas by the World Health Organization." (PMID 33087075, 2020). "Intriguingly, the deregulated expression of BCL6 is associated with an increased malignancy of multiple cancer entities, such as lymphomas, breast cancer, and ovarian cancer, which correlates with increased invasion and metastatic rates." (PMID 33182312, 2020). "Whereas systemic DLBCL with co-expression of c-Myc and Bcl-2 (double-expressor) and/or co-rearrangement of MYC and BCL2 and/or BCL6 (double or triple hit lymphoma) has been associated with a worse prognosis, the findings were inconclusive for PCNS DLBCL." (PMID 33322508, 2020). "BCL6 is a transcription factor commonly mutated in lymphoma cells where it can epigenetically regulate a number of its targets through modifications in chromatin accessibility at promoter and enhancer regions." (PMID 31380371, 2019). "We aimed to address the impact of the lymphoma type, EZH2 mutation status, as well as MYC, BCL2 and BCL6 translocations on the sensitivity of the lymphoma cell lines to DZNep-mediated apoptosis." (PMID 31419226, 2019). "Many lymphoma mutations have the commonality of enhancing the oncogenic functions of BCL6, or overcoming some of its tumor suppressive effects." (PMID 30874354, 2019). "Double-hit (DH) lymphomas, defined as lymphomas with MYC translocation combined with BCL-2 or BCL6 translocation, are among the most aggressive variants." (PMID 30287880, 2018). "Due to the mutation of BCL6 promotor, the overexpression of this gene was frequently found in lymphoma especially in the diffuse large B-cell lymphoma (DLBCL)." (PMID 30420967, 2018). "BCL6 is a zinc-finger transcription factor overexpressed, translocated or mutated in several lymphomas among which diffuse large B-cell (DLBCL) and follicular (FL) lymphomas and in glioma." (PMID 29921764, 2018). "BCL6 chromosomal rearrangements and/or mutations are associated with human lymphomas, up to 73% in diffuse large B-cell lymphoma." (PMID 28401061, 2017). "Deregulated and increased Myc and Bcl proteins, such as Bcl2 and Bcl6, are associated with particularly aggressive lymphoma types." (PMID 25987903, 2015). "79–6 is also functionally active in vivo and causes apoptosis of BCL6 dependent lymphoma cell lines." (PMID 24595451, 2014). "Peptide or small molecule inhibitors, which prevent the association of SMRT with BCL6, inhibit transcriptional repression and cause apoptosis of lymphoma cells in vitro and in vivo." (PMID 24595451, 2014).
lymphoma (continued). "The peptide prevents normal germinal center formation in mice and when administered to BCL6 dependent cell lines or primary lymphoma cells causes apoptosis." (PMID 24595451, 2014). "Mainly implicated in lymphomas, Bcl6 expression is also associated with epithelial cancers, and can promote self-renewal and repress differentiation of both B cells and mammary epithelia." (PMID 23874226, 2013). "Of importance, deregulated BCL6 expression is associated with lymphoma genesis, at least in part by allowing the occurrence of genetic aberrations in an environment unresponsive to DNA damage checkpoints and by interfering with the differentiation processes." (PMID 22929622, 2012). "Interestingly, BCL6 overexpression extends beyond lymphomas, being implicated in breast cancer, ovarian cancer [, glioma, chronic myeloid leukemia, non-small cell lung cancer and so on." (PMID 39815148, 2025). "As a highly conserved transcript suppressor, BCL6 was reported to act as proto-oncogene by affecting cancer hallmark pathways including proliferation, DNA repair, anti-apoptosis, and enable cancer cells to adapt to stress in both lymphoma and solid tumor." (PMID 38956432, 2024). "Next, we sought to determine whether lymphoma growth upon loss of Fbw7 is biologically dependent on Bcl6." (PMID 38485719, 2024). "Additionally, dysregulation of BCL6 has been implicated in various diseases, including lymphoma and autoimmune disorders." (PMID 37373354, 2023). "The prognostic value of cell-cycle associated markers in disease-free survival and lymphoma related death has been investigated, and lymphoma associated transcription factor BCL-6, MUM1/IRF4 and MIB1/Ki-67 have been associated with a higher risk of disseminated disease." (PMID 35882984, 2023). "Importantly, BCL6 is implicated in the pathogenesis of human lymphomas, such as the diffuse large B-cell type." (PMID 35906392, 2022). "As DLBCL can be driven by BCL6 translocations or hyperactive RAS signaling, the appearance of frequent mutations in Kras or Bcor, which encodes a repressor of BCL-6, as tertiary drivers in Eμ-Myc lymphomas might explain DLBCL-like gene expression signatures." (PMID 36611833, 2022). "These Hodgkin cells may also express markers of the associated lymphoma such as BCL2/BCL6 for follicular lymphoma and Cyclin D1 for mantle cell lymphoma, which may be combined with BCL2/BCL6 and CCND1 rearrangements in both contingents, respectively." (PMID 36428786, 2022). "These outcomes establish that resveratrol inhibits a BCL6-linked pathway and propose that loss of BCL6, a transcriptional repressor frequently translocated in lymphoma expression, may signify a main event primary to the proliferative activities of resveratrol." (PMID 35566016, 2022). "We next determined whether conditional loss of BCL6 affects lymphoma cell proliferation and/or survival in vitro." (PMID 32180900, 2020). "A chromosomal translocation at the Bcl6 locus is reported to cause lymphoma." (PMID 32546802, 2020). "For example, the presence of mutations in the 5’-noncoding region of the BCL6 gene (a marker of B-cell transition through the germinal center) in a significant subset of PCNS lymphomas suggests that this lymphoma might be derived from germinal center Bcells." (PMID 33322508, 2020). "Together, these studies suggest that the mutations of KMT2D may also be contribute to lymphoma in part via the epigenetic deregulation of BCL6 target genes." (PMID 31788471, 2019). "For instance, RIP-Seq analysis in lymphoma cells indicated that nuclear eIF4E binds over 3000 mRNAs that encode proteins acting in lymphoma-sustaining pathways such as B-cell receptor signaling (Bcl2, Bcl6) and DNA methylation/epigenetic regulation (DNMT1, DNMT3A, HDAC1)." (PMID 30455716, 2018). "Conversely, deregulated expression of BCL6 is a pathogenic event in many lymphomas." (PMID 27764808, 2016).